PRR4 (proline rich 4)
Synonyms: LPRP; PROL4
Tractability: Antibody: UniProt places it where antibodies can reach, with medium confidence; UniProt predicts a signal peptide or a membrane-spanning region; its Gene Ontology location is reachable by antibodies, with medium confidence.
Gene: Protein-coding gene on chromosome 12 (10,845,849 to 11,171,600, reverse strand). Ensembl gene ENSG00000111215.
Subcellular location: Secreted
Gene Ontology:
Molecular function: protein binding
Biological process: visual perception
Cellular component: extracellular region
Genetic constraint (gnomAD): Loss-of-function variants: 5 observed, 5.23 expected, observed/expected ratio (o/e) 0.96, 90% interval 0.49 to 1.78. That is too few expected variants to judge how well the gene tolerates losing a copy. Missense variants: 144 observed, 126.09 expected, observed/expected ratio (o/e) 1.14, 90% interval 1 to 1.31. Synonymous variants: 43 observed, 43.96 expected, observed/expected ratio (o/e) 0.98, 90% interval 0.76 to 1.26.
Homologues: Orthologues: chimpanzee PRR4 (99% identical). Paralogues in human: PRH2 (45% identical), PRH1 (42% identical), PRB3 (40% identical), PRB2 (39% identical), PRB4 (37% identical), PRB1 (35% identical).
Diseases named in the same sentence as PRR4 in open-access papers:
PRR4 is named in the same sentence as 21 diseases in open-access papers, as found by Europe PMC text mining. Sharing a sentence is not in itself a finding about the gene and the disease. The quoted sentences say what the papers report.
dry eye syndrome (5 papers, 2012 to 2022). A syndrome characterized by dryness of the cornea and conjunctiva. "Some of our saDMPs were located in genes known to show sex by age effects, such as PRR4, a gene associated with dry eye syndrome." (PMID 35568878, 2022). "In contrast, lachrymal proline-rich 4 protein in tears specifically from lachrymal gland secretion were significantly downregulated in all types of dry eye, correlating with disease severity." (PMID 23761727, 2013).
asthma (3 papers, 2021 to 2026). "After adjusting for confounding factors such as gender and age, these five genes (CEBPE, HDC, IRAK3, PRR4, and SOD2) were still independent risk factors for asthma." (PMID 41602038, 2026). "For the path where PM2.5 affects asthma through PRR4, the indirect effect was 0.012 [95% CI (0.033, 0.1), p = 0.475], with an SE of 0.017 and a z/t value of 0.714." (PMID 41602038, 2026). "By conducting bioinformatics analysis, we identified five genes (CEBPE, HDC, IRAK3, PRR4, and SOD2) associated with asthma." (PMID 41602038, 2026). "We identified 8 key genes (LOC100132287, CEACAM5, PRR4, CPA3, POSTN, LYPD2, TCN1, and SCGB3A1) associated with asthma by combining the LASSO regression model and the SVM-RFE method." (PMID 39963184, 2025). "Zhong revealed that PRR4 is a specific asthma gene through bioinformatics approaches." (PMID 41602038, 2026). "The role of the gene PRR4 in asthma require further verification." (PMID 39963184, 2025). "The results revealed that five genes of interest (CEBPE, HDC, IRAK3, PRR4, and SOD2) showed a strong mediating effect between PM2.5 and the onset of asthma, suggesting that PM2.5 may alter the expression of these genes, thereby causing the onset of asthma." (PMID 41602038, 2026). "In this study, a mediation effect analysis was conducted to elucidate the potential mediating mechanisms between PM2.5 and the onset of asthma, involving several potential mediators, including CEBPE, HDC, IRAK3, PRR4, and SOD2." (PMID 41602038, 2026). "This study provided evidence that CEBPE, HDC, IRAK3, PRR4, and SOD2 mediate the connection between PM2.5 and the onset of asthma." (PMID 41602038, 2026). "We further used a one-to-one format for comparison and validated with the GSE63142 dataset The genes CEACAM5, PRR4, CPA3, POSTN, TCN1, CST1 (Cystatin-SN), CLCA1, TPSAB1 and NOS2 (Nitric oxide synthase 2) were highly expressed in patients with asthma." (PMID 39963184, 2025). "PRR4, TCN1, CST1, CLCA1, and NOS2 were also highly expressed in patients with asthma in GSE158752 dataset." (PMID 39963184, 2025). "To determine the role of these key genes in the occurrence of asthma caused by environmental pollution, we provided strong evidence that the expression of genes of interest (CEBPE, HDC, IRAK3, PRR4, and SOD2) increased significantly in 160 participants with asthma." (PMID 41602038, 2026). "Finally, five genes (CEBPE, HDC, IRAK3, PRR4, and SOD2) were identified as overlapping features across all three algorithms, as illustrated in the Venn diagram, and were thus considered robust candidate biomarkers for asthma." (PMID 41602038, 2026).
autoimmune disease (1 paper, 2024). A disorder resulting from loss of function or tissue destruction of an organ or multiple organs, arising from humoral or cellular immune responses of the individual to their own tissue constituents. "Unsurprisingly for this autoimmune disease, invasive lymphocytes replaced PRR4+CST3+WFDC2− seromucous acinar cells nearly one-to-one." (PMID 38196575, 2024).
bladder cancers (1 paper, 2025). "TM4SF1 is a promising target because its expression is not limited to HV bladder cancers and its negative association with PVRL4/PRR4 expression suggests that targeted therapy against TM4SF1 could complement existing targeted agents." (PMID 40527915, 2025).
Down syndrome (1 paper, 2020). "We experimentally validated 2 regions mapping in FIGN and PRR4 genes and showed sex-specific deviations of their methylation patterns in models of decelerated (centenarians) and accelerated (Down syndrome) aging." (PMID 33276343, 2020). "In particular, a subset of centenarian males showed a “feminization” of FIGN methylation values, while females with Down syndrome showed a “masculinization” of PRR4 methylation values." (PMID 33276343, 2020).
primary ciliary dyskinesia (1 paper, 2022). A rare, genetically heterogeneous, primarily respiratory disorder characterized by chronic upper and lower respiratory tract disease. "In diseases like non-CF bronchiectasis (NCFB) and primary ciliary dyskinesia (PCD), the sputum concentration of PRR4 was significantly elevated compared to disease controls, which is consistent with SMG hypersecretion." (PMID 36142171, 2022).
tumor (2 papers, 2003 to 2024). "Among the downregulated DEGs, four genes (LAMA1, ASPRV1, IL1B, PRR4) displayed reduced expression, while two genes (CCDC157, RP1) showcased elevated expression in tumor compared to normal tissue, respectively." (PMID 39062832, 2024).
PRR4 also shares sentences with these, for which no sentence is quoted: dry eye (2 papers); breast carcinoma (1); cancer (1); chronic obstructive pulmonary disease (1); diabetic proliferative retinopathy (1); diabetic retinopathy (1); infection (1); lupus nephritis (1); malignant brain tumors (1); multiple sclerosis (1); nasal polyps (1); primary open angle glaucoma (1); rheumatoid arthritis (1); Stevens-Johnson syndrome (1).